CD4 (CD4 molecule)
Diseases named in the same sentence as CD4 in open-access papers (continued):
Sharing a sentence is not in itself a finding about the gene and the disease.
malignant hypertension (2 papers, 2016 to 2024). Severe hypertension that is characterized by rapid onset of extremely high blood pressure and hypertension-mediated organ damage. "CD4+CD25+ cells may play a key role in the pathogenesis of primary malignant hypertension related kidney injury." (PMID 27278520, 2016).
melanosis (2 papers, 2013 to 2025). "While specifically mentioning CD4+ T cells, the elevated IL-17 levels observed in melasma lesions strongly suggest the involvement of T helper 17 (Th17) cells, which are known producers of IL-17." (PMID 41154805, 2025). "Melasma lesions are characterized by infiltrates of various immune cells, including CD4+ T cells and macrophages, alongside mast cells." (PMID 41154805, 2025). "In addition, melasma lesions harbor subclinical inflammation: infiltrates of CD4+ T cells, macrophages, and mast cells are visible, accompanied by elevated IL-17 and COX-2, implying an immune-driven component sustains pigment production." (PMID 41154805, 2025).
metastatic prostate carcinoma (2 papers, 2001 to 2021). A carcinoma that arises from the prostate gland and has spread to other anatomic sites. "In accordance with these findings, the expression of proliferation markers on CD4+ T cells 2 weeks after therapy initiation of ipilimumab and GM-CSF was increased in patients with metastatic prostate cancer." (PMID 34360781, 2021).
mismatch-repair deficiency (2 papers, 2022 to 2023). "The levels of CD4+ and CD8+ T cells in TME were found significantly higher than those in the CRC tumor, while the patients with mismatch-repair deficiency/microsatellite instability were accompanied with high levels of CD4+ and CD8+ T cells." (PMID 35433435, 2022).
molluscum contagiosum (2 papers, 2013 to 2023). A common, benign, usually self-limited viral infection of the skin and occasionally the conjunctivae by a poxvirus (molluscum contagiosum virus). "Molluscum contagiosum and herpes zoster ophthalmicus were common in patients with a CD4+ T cell count of 200–499 cells/μl." (PMID 23710936, 2013). "Patients with a CD4+ level of less than 200 cells/L frequently developed HIV retinopathy and conjunctival micro vasculopathy, whereas patients with a CD4+ count of 200–499 cells/L frequently developed HZO and molluscum contagiosum." (PMID 37763724, 2023). "HIV retinopathy and conjunctival microvasculopathy were common in patient with CD4+ count of <200 cells/μl while HZO and molluscum contagiosum were common in patients with CD4+ count of 200–499 cells/μl." (PMID 23710936, 2013).
multidrug-resistant TB (2 papers, 2015 to 2022). "Mortality was associated with never receiving ART (adjusted hazard ratio (aHR) 6.0, CI 2.1–18.1), CD4 count ≤100 (aHR 2.1, CI 1.0–4.5), and multidrug-resistant tuberculosis (MDR-TB) with second-line resistance (aHR 2.5, CI 1.1–5.4)." (PMID 26555134, 2015). "One patient with multidrug-resistant TB (MDR-TB), CD4 of 52 cells/mm3 and five different positive TB tests was asymptomatic." (PMID 35197162, 2022).
myelofibrosis (2 papers, 2021 to 2022). A partial or complete replacement of the bone marrow stroma by fibrous tissue. "Internal consistency analysis regarding evaluation of the immunohistochemical markers yielded good or excellent results for myelofibrosis, nestin niches, CD34-positive blast counts, and counting of granzyme B, T-bet, FoxP3, CD3, CD4, CD8, and E-cadherin positive cells." (PMID 33704530, 2021).
myonecrosis (2 papers, 2021 to 2025). "The histological findings in patients with anti-HMG-CoA reductase associated myonecrosis include degeneration of muscle fibers, presence of predominantly M2 macrophages that play a role in muscle regeneration and repair, and CD4+ and CD8+ T cells." (PMID 40162298, 2025). "We induced a myonecrosis with CTX injection in TLA to cause an immune challenge which is known to be accompanied by an accumulation of CD4+ T cells in injured SKM." (PMID 33815130, 2021).
myopia (2 papers, 2023 to 2024). "Our study showed that the proportions of inactivated mast cells and M2 macrophages increased and the proportions of activated dendritic cells, activated mast cells, plasma cells, and CD4 T cells were lower in people with myopia." (PMID 37747014, 2023).
nasal obstruction (2 papers, 2016 to 2020). "While CD4+ T-cells of patients with upper airway infections showed a Th1 dominance, the group with only nasal obstruction showed an optimal Th1/Th17 ratio of one." (PMID 32849561, 2020). "Further clinical and animal investigations on the role of CD4+ T cell-derived neurotransmitters along with monitoring nasal obstruction, secretion, and sneezing response is important to understand the detailed pathogenesis of NHR." (PMID 26752722, 2016). "Although the physiological process of nasal obstruction and secretion is different from that of sneezing, these neural transmitters might be involved in the CD4+ T cell-mediated enhancement of sneezing response in AR." (PMID 26752722, 2016).
neuroendocrine tumor (2 papers, 2021 to 2024). "Four people were excluded; in 3 nebulised pentamidine prophylaxis was administered for non-HIV associated reasons (2 post renal transplant, during chemotherapy for a neuroendocrine tumour in 1: all 3 had undetectable viral loads and CD4 counts >200 cells/ μ L): one further patient had HIV-2." (PMID 38606484, 2024).
obstructive sleep apnea (2 papers, 2022 to 2025). "We recently showed that obstructive sleep apnea syndrome (OSAS) patients reveal a redistribution of monocyte subsets and a subsequently affected imbalance in the PD-1/PD-L1-mediated communication with CD4/CD8 T cells." (PMID 35740384, 2022).
onchocerciasis (2 papers, 2018 to 2020). Onchocerciasis is a form of filariasis, caused by the parasitic worm Onchocerca volvulus, transmitted by the black fly. "On the one hand, the known interaction of specific HLA class II molecules with helper CD4+ T cells could induce beneficial protection against Ov infection, Onchocerciasis and NS." (PMID 32639997, 2020).
oncocytoma (2 papers, 2022 to 2025). "CD4 and CD8 RCC TILs from ccRCC showed increased fatty acid uptake as compared to benign kidney tumors (oncocytoma and angiomyolipoma) and peripheral blood T cells." (PMID 40902455, 2025).
otitis media with effusion (2 papers, 2012 to 2025). Otitis media associated with accumulation of fluid in the middle ear. "Previously, we have found that hypertrophic adenoid of children with otitis media with effusion exhibits markedly lower percentages of CD4+ and CD8+ T cells." (PMID 22382400, 2012). "The mean percentage of CD4+ lymphocytes with CD132 expression in hypertrophic adenoid in children with otitis media with effusion was 45.44 ± 8.13%, being statistically significantly higher (p < 0.05) than in the reference group (HA 39.91 ± 7.54%)." (PMID 22382400, 2012). "The mean percentage of CD4+ T cells with CD127 expression in hypertrophic adenoid with otitis media with effusion (OME) was 56.37 ± 5.73%, being statistically significantly higher (p < 0.005) than in the reference group (HA 48.18 ± 9.41%)." (PMID 22382400, 2012). "The aim of this study was to evaluate the percentage of lymphocytes T (CD4+ and CD8+) with IL-7R (CD127 and CD132) expression in hypertrophic adenoid in children suffering with otitis media with effusion for a duration of 3 months." (PMID 22382400, 2012). "The percentage of CD4+ and CD8+ T cells with CD127 receptor expression in hypertrophic adenoid of children with otitis media with effusion was statistically significantly higher than in hypertrophic adenoid group." (PMID 22382400, 2012). "The percentage of CD4+ and CD8+ T cells with CD127 receptor expression in hypertrophic adenoid in children with otitis media with effusion was statistically significantly higher than in HA group." (PMID 22382400, 2012). "The study objective was to assess the percentage of lymphocytes T (CD4+ and CD8+) with IL-7R (CD127 and CD132) expression in the group of children with hypertrophic adenoid in children with otitis media with effusion who suffer of 3 months’ duration." (PMID 22382400, 2012).
ovarian endometriosis (2 papers, 2010 to 2023). A non-neoplastic disorder characterized by the growth of endometrial tissue in the ovaries. "We did not observe any differences over the course of the menstrual cycle in the percentage of FOXP3+ positive cells within the subpopulation of CD4+T lymphocytes in ectopic endometrium in the tissue samples from the group of patients with ovarian endometriosis." (PMID 20923543, 2010).
Pallor (2 papers, 2014 to 2024). "The gene sets encompass numerous genes previously implicated in the pathogenesis of SSc, such as Acta2, Col1a1, Col3a1, Smad3, Ctgf, Msr1, Cd4, Cd8a and Cd68, supporting the potential of anti-PRMT5 in induction of SSc-like skin changes." (PMID 38684324, 2024).
pancolitis (2 papers, 2021). Ulcerative colitis that involves the entire colon. "Our data demonstrate that the patient’s CD4+ T cells exhibit constitutive activation of the IL-2R-pSTAT5 pathway leading to hyper-responsiveness of CD4+ effector T cells possibly predisposing to T-cell driven pancolitis." (PMID 34226674, 2021).
papilledema (2 papers, 2009 to 2024). "In contrast, an acute primary MOG-IgG/CD4 + T-cells-related longitudinal inflammation of the distal optic nerve causes a global perineural contrast enhancement with papilledema and equal affection of all ON fibers in MOGAD." (PMID 39249105, 2024).
pleural tumor (2 papers, 2024). "The scRNA-seq data also demonstrated that CD4+ T cells from C1qa-/- mice had a phenotype with enhanced helper-like features, while CD8+ T cells displayed a phenotype with increased effector-like characteristics and decreased exhaustion in both MPE and pleural tumor cells." (PMID 39664577, 2024).
pneumonic plague (2 papers, 2023). A plague in which the bacteria have infected the lungs. "Another study indicated that the intratracheal transfer of lung CD4+ and CD8+ TRM cells conferred comprehensive protection against pneumonic plague in naive recipient mice." (PMID 37154735, 2023).
podoconiosis (2 papers, 2024). A disease of the lymphatic vessels of the lower extremities that is caused by chronic exposure to irritant soils. "We also found a significant reduction in CD4% in the podoconiosis patient compared to healthy controls (AMD = -3.39, 95% CI: -6.39, -0.40; p = 0.027)." (PMID 39689160, 2024). "Peripheral blood immunophenotyping of T cells indicated podoconiosis patients had significantly higher CD4 and CD8 T cell surface HLA-DR expression compared to healthy controls while CD62L expression was significantly lower." (PMID 38448477, 2024). "The final significant marker was the decreased percentage of CD4+ T cells among podoconiosis patients." (PMID 39689160, 2024). "Immunohistochemistry analysis of Price’s archival lymph node samples showed that CD4 T lymphocytes were the predominantly infiltrating cells from podoconiosis patient biopsy samples, suggesting these T cells could play a role in development of the disease." (PMID 38448477, 2024). "We have presented evidence of activation of T cells in podoconiosis patients compared to healthy controls, with higher levels of HLA-DR expression on both CD4 and CD8 T-cell subsets while CD62L expression was lower in podoconiosis patients." (PMID 38448477, 2024). "The average percentage of CD4 and CD8 T cells expressing HLA-DR was significantly higher in podoconiosis patients compared to healthy controls (P < 0.001 with median of 10.7% vs 7.1% for HLA-DR on CD4 and 23.4% vs 15.8% for HLA-DR expression on CD8 cells, respectively)." (PMID 38448477, 2024).
polyarteritis nodosa (2 papers, 2021). Polyarteritis nodosa (PAN) is a rare, clinically heterogeneous, rheumatologic disease characterized by necrotizing inflammatory lesions affecting small- and medium-sized blood vessels. "However, some hints of a potential role of JAK/STAT may come from the evidence of an upregulation of STAT3 in the PB CD4+ and CD8+ T cells of polyarteritis nodosa (PAN) patients and of increased levels of CXCL10 (a STAT induced gene) in active Kawasaki disease." (PMID 33854436, 2021). "In polyarteritis nodosa (PAN) patients, rather than the number of CD4+ T cells infiltrating, that of CD8+ T cells in the arteries intima was significantly higher." (PMID 34429489, 2021).
polyarticular JIA (2 papers, 2019 to 2021). "The same group also studied signaling abnormalities in polyarticular JIA and found that treatment-naïve patients displayed enhanced IFN-γ signaling in CD4 T cells and monocytes." (PMID 31231652, 2019). "In the case of JIA, treatment-naive polyarticular JIA patients were found to have enhanced responsiveness to IFN-γ stimulation compared with controls (i.e., increased STAT1 and/or STAT3 phosphorylation in subsets of CD4 T cells and classical monocytes)." (PMID 33921679, 2021).
pouchitis (2 papers, 2011 to 2024). Acute inflammation in the intestinal mucosa of the continent ileal reservoir (or pouch) in patients who have undergone ileostomy and restorative proctocolectomy (proctocolectomy, restorative). "VSL#3-treated patients showed a significant reduction in pouchitis disease activity index score and a significant increase in the percentage of infiltrating CD4+CD25high and CD4+ LAP-positive cells to the lamina propria, compared with baseline values." (PMID 22254115, 2011).
prion disease (2 papers, 2017 to 2025). A transmissible disease that is caused by a protein that is able to induce abnormal folding of normal cellular proteins, leading to characteristic spongiform brain changes, which are associated with neuronal loss without an inflammatory response. "In this regard, stimulating regulatory function of infiltrating CD4+ T cells may act therapeutically in MS, PD and to a certain degree in ALS, while in AD and prion disease CD4+ T cells already seem regulatory and may benefit from a more pro-inflammatory T cell phenotype." (PMID 29422891, 2017).
pseudolymphoma (2 papers, 2024 to 2025). A neoplastic process that resembles a malignant lymphoma, but has a benign course. "From a diagnostic point of view, both the reactivity and atypical presentation of CD4+ lymphocytes during the inflammation process can be misdiagnosed as pseudolymphoma." (PMID 37657958, 2024). "Our patient’s presentation - polymorphous infiltrate, modest CD7 reduction, CD4-predominant dermal infiltrate, negative TCR clonality, and recent HCTZ exposure supported the pseudolymphoma LDR diagnosis over MF." (PMID 41550319, 2025).
Psoriasiform dermatitis (2 papers, 2016 to 2018). A skin abnormality characterized by redness and irritation, with thick, red skin that displays flaky, silver-white patches (scales). "The IMQ model of psoriasiform dermatitis is driven by cytokine secreting CD4+ T cells of the lymphoid compartment in addition to CD11b+ myeloid cells." (PMID 30262916, 2018). "Analysis of gene-modified mice suggests that the initiation of IMQ-induced psoriasiform dermatitis involves the TLR7- and IFNAR1-mediated signaling cascades, whereas the activation of CD4+ Teff cells through costimulation by APCs contributes to the disease progression." (PMID 27075414, 2016).
pterygium (2 papers, 2021 to 2024). A wedge-shaped fibrovascular lesion arising from the bulbar conjunctiva and extending to the cornea. "In addition, pterygium samples were characterized by the enrichment of CD4+ memory T–cells, common lymphoid progenitor (CLP) cells, classical dendritic cells (cDC), preadipocytes, CD8+ T-cells, M2 macrophages and chondrocytes." (PMID 35174178, 2021). "Previous studies have demonstrated increased infiltration of CD4+ and CD8+ T lymphocytes in pterygium tissue when compared with normal conjunctival tissue, indicating that some of the GrB may come from other cell types as well." (PMID 39201366, 2024).
pulpitis (2 papers, 2023). Inflammation of the dental pulp. "Compared with the control group, the majority of the signatures were significantly changed among pulpitis tissues, including those of activated B cells and activated CD4 and CD8 T cells." (PMID 37275855, 2023). "CD4+T cells could promote the number of B cells via binding specific immunoglobulin on B cells in pulpitis." (PMID 37238161, 2023).
Pyoderma (2 papers, 2016 to 2020). Any manifestation of a skin disease associated with the production of pus. "On the other hand, Fernandes and Bhat reported statistically significant association with CD4 T-cell count in pyodermas, dermatophytoses and papular pruritic eruptions." (PMID 32850174, 2020). "In German shepherd dogs suffering from pyoderma (GSP) the percentage of CD4+ cells decreased, CD8+ cells increased and ratio CD4+/CD8+ decreased in comparison to healthy dogs." (PMID 27553600, 2016).
pyomyositis (2 papers, 2013 to 2015). Pyomyositis (PM) is a rare primary bacterial infection of the skeletal muscle, usually resulting from hematogenous spread or due to muscle injury, and characterized by pain and tenderness in the affected muscle, fever and abscess formation. "Not all HIV positive patients have an increased risk of developing pyomyositis but rather those with low CD4 counts of less than 250 cells per ml that developed pyomyositis." (PMID 26052503, 2015). "A Medline review by Crum of bacterial pyomyositis among HIV and non-HIV infected persons in the United States showed that pyomyositis among HIV-infected persons is more often associated with end-stage disease (CD4 < 50 cells/mm) with an increased risk for recurrence." (PMID 24307959, 2013).
radiation pneumonitis (2 papers, 2020 to 2023). Inflammation of the lung due to harmful effects of ionizing or non-ionizing radiation. "The lower peripheral blood levels of lymphocytes and CD4+ T lymphocyte were associated with an increased risk of radiation pneumonitis, which was validated by this mice model." (PMID 36959779, 2023). "Values of lymphocytes and CD4+ T lymphocyte subsets proved as independent predictors of radiation pneumonitis." (PMID 36959779, 2023). "Therefore, decrease in lymphocyte and CD4+ T lymphocyte was able to act as a predictor of radiation pneumonitis in patients who received thoracic radiotherapy." (PMID 32207253, 2020).
Rectal prolapse (2 papers, 2018 to 2019). Protrusion of the rectal mucous membrane through the anus. "In spontaneous disease, intestinal intraepithelial CD8+ but much fewer CD4+, T-cells from Gab2/3−/− mice with rectal prolapse were more proliferative." (PMID 30936879, 2019).
respiratory syncytial virus infection (2 papers, 2020 to 2025). "Similar modulatory effects on T-cell subsets have been documented previously; for example, baicalin restored CD4+/CD8+ ratios disrupted by respiratory syncytial virus infections." (PMID 40406095, 2025). "Moreover, during human respiratory syncytial virus infection, increased populations of CD4+ and CD8+ T cells exhibiting effector functions have been observed in the BAL of infected patients." (PMID 32404209, 2020).
retinal disease (2 papers, 2021 to 2025). "However, direct mechanistic evidence linking combined CD4+ and CD8+ T-cell impairment to the development of retinal disease remains scarce." (PMID 41179870, 2025).
Rickettsia infection (2 papers, 2017 to 2020). "Our laboratory confirmed the effectiveness of both CD4+ and CD8+ T lymphocytes, especially CD8+ T cells, in Rickettsia infection and clearance through depletion and adoptive transfer of immune CD4+ or CD8+ T lymphocytes." (PMID 28723951, 2017).
sacroiliitis (2 papers, 2014 to 2019). "The pathology of sacroiliitis is associated with extensive infiltration of inflammatory cells, such as CD4+ and CD8+ T cells and macrophages." (PMID 31533751, 2019).